ATG5 (autophagy related 5)
Diseases named in the same sentence as ATG5 in open-access papers (continued):
Sharing a sentence is not in itself a finding about the gene and the disease.
tumor (continued). "The deletion of ATG5 results in a tumor-suppressive phenotype, akin to the presence of heterozygote mutation of BECN1 in cancer models, whereas only benign hepatomas are observed in a mouse liver model." (PMID 38067169, 2023). "In both syngeneic models, deletion of Atg5 in blood ECs yielded a similar reduction in tumor burden." (PMID 38009521, 2023). "MiR-181a was found to target many genes in the autophagy pathway; one of them is Atg5 which is a target of miR-181a in suppressing the autophagy of tumor cells." (PMID 37456780, 2023). "Autophagy inhibition by targeting Beclin1 or Atg5 restored granzyme B levels in hypoxic cells in vitro and induced tumor regression in vivo facilitating NK-mediated tumor cell killing." (PMID 38071322, 2023). "The expression of Ki-67 (quantified as the percentage of positive cells) and ATG5 (quantified as the mean density) in tumor tissues were evaluated by IHC staining." (PMID 37474520, 2023). "Similar to what was observed upon deletion of Atg5, loss of Atg12 or Atg9 in ECs increased p62 granularity in CD31+ tumor vessels indicating reduced autophagy flux (Fig EV1D and E)." (PMID 38009521, 2023). "The C2-tumor cluster had high autophagy (ATG5, MAP1LC3B), high plasticity (SOX4, CD164) and low mTORC1 activity (RPS6, MLST8), characteristics of early paligenosis (stages 1-2)." (PMID 36788228, 2023). "Autophagy-competent mice receiving subtherapeutic doses of atg5-/- T cells also demonstrate controlled tumor growth." (PMID 37675121, 2023). "Deletion of ATG5 results in a tumor-suppressive phenotype, similar to abnormal BECN1 in cancer models, but only benign hepatomas in a mouse liver model." (PMID 36831455, 2023). "The results revealed that Ki-67 and ATG5 expression levels were significantly increased in the tumor tissues from oe-ciR group." (PMID 37474520, 2023). "Various mechanisms have been proposed based on tumor conditions or the microenvironment, but most involve Atg5 or Atg7." (PMID 38067169, 2023). "This likely accounts for the reduced tumor burden in Atg5/STINGBECDKO mice, to a similar extent to Atg5BECDKO mice." (PMID 38009521, 2023). "Next, we extracted total RNA from tumor tissues to investigate the content of miR-205-5p and ATG5 mRNA expression by qRT‒PCR." (PMID 37474520, 2023). "Studies have shown that in bone marrow chimeras with ATG5-deficient donor cells, there is a significant increase in IFN-γ and TNFα-producing CD8+ T cells in tumor-infiltrating lymphocytes, leading to improved tumor control." (PMID 37675121, 2023). "Mechanistically, miR-567 was incorporated into tumor-derived exosomes and reversed drug resistance via inhibiting autophagy-related 5 (ATG5) expression." (PMID 35592419, 2022). "In contrast, a significant reduction in tumor growth, starting from Day 16 following tumor cell inoculation was observed in Atg5flox/flox recipient mice, compared to Atg5+/+ recipient mice." (PMID 35966597, 2022). "This novel syngeneic tumor model enables us to show for the first time that host ATG5-dependent autophagy promotes tumor progression by suppressing the antitumor immune response, independently of the autophagy genotypes of donor tumor cells." (PMID 35966597, 2022). "In the present study, miR-30a-3p directly targeted Beclin 1 and ATG5/12, which separately participate in the regulation of vesicle nucleation and elongation, leading to increased chemosensitivity and impaired tumor progression." (PMID 35449123, 2022). "The homozygous knockout of ATG5 in mice harboring KRASG12D supported tumor initiation but prevented PDAC tumors from progressing into more malignant states." (PMID 35884592, 2022). "Whereas, the heterozygous knockout of ATG5 in the same mouse model increased tumor incidence, malignancy and metastatic potential in PDAC by enhancing neoplastic migration and invasion when compared to the homozygous ATG knockout or KRASG12D control mice." (PMID 35884592, 2022).
tumor (continued). "In KRASG12V;Atg5∆/∆ tumor cells, the Atg5 expression was ablated and the conversion of microtubule-associated protein 1A/1B-light chain 3 (LC3)-I to the lipidated form of LC3B-II was lower than KRASG12V;Atg5+/+ MST cells, supporting the deletion of ATG5." (PMID 35966597, 2022). "Knock down of CD95, Beclin1, ATG5 or eIF2α significantly reduced tumor cell killing by the drug combination." (PMID 35035775, 2022). "Subsequent studies were focused on analyzing the TME residents in tumor-bearing Atg5+/+ mice and Atg5flox/flox mice on Day 14 and on Day 25, respectively." (PMID 35966597, 2022). "Consistently, terminal necropsy verified a general disappearance in the size of metastatic nodules in the viscera, peritoneal wall, and omentum, but tumor growth obviously recovered with ATG5 depletion." (PMID 36481655, 2022). "Histopathological examination revealed lower levels of LC3-II, ATG5/12, and Beclin 1 expression and higher levels of p62 expression in the tumor tissue of mice treated with hsa-miR-30a-3p compared with those that were not." (PMID 35449123, 2022). "Studies have indicated that overexpression of Atg5 protein can sensitize tumor cells to chemotherapy." (PMID 35359388, 2022). "Higher Treg infiltrate within SMG TME of tumor-bearing Atg5+/+ mice would inhibit CD8+ cytotoxic T cells, leading to a tumor progression phenotype." (PMID 35966597, 2022). "A heatmap showed trends and percentages of tumor-infiltrating immune cells in high and low ATG5 expression HNSCC samples." (PMID 36185455, 2022). "Together, our data suggests that autophagy promotes the expansion of both M1 and M2 TAMs in SMGs of tumor-bearing Atg5+/+ recipient mice at the later stage post-tumor cell inoculation." (PMID 35966597, 2022). "Knock down of ATM, AMPKα or the autophagy-regulatory proteins Beclin1 or ATG5 significantly reduced tumor cell killing." (PMID 36408163, 2022). "Knock down of eIF2α, Beclin1 or ATG5 also reduced tumor cell death to a similar extent as did over-expression of FLIP-s whereas knock down of ATM less effective." (PMID 36408163, 2022). "We found that the tumor volume and tumor weight in tumor-bearing Atg5flox/flox mice treated with an anti-CD8 antibody significantly increased, comparable to those in IgG-treated tumor-bearing Atg5+/+ mice, over IgG-treated tumor-bearing Atg5flox/flox mice." (PMID 35966597, 2022). "Subsequently, we assessed the anti-tumor effect of drugs in vitro and observed that knock out ATG5 had a remarked promotion of cell death in whatever either drug group or combination of both drugs." (PMID 36353537, 2022). "Accordingly, SMG tumor weights from Atg5flox/flox recipient mice were significantly lower than those from Atg5+/+ recipient mice at the later time-point when tumors were harvested." (PMID 35966597, 2022). "For the first time, we identified that miR124-3p and miR766-3p attenuate expression of CREBRF and NR3C2, respectively, in HNSCC, which promotes aggressive tumor behavior by inducing the signaling axes CREB3/ATG5 and β-catenin/c-Myc." (PMID 36358691, 2022). "In contrast, silencing the ATG5 gene with short interfering RNA made tumor cells partially resistant to chemotherapy." (PMID 35359388, 2022). "Instead, we provide evidence that impaired autophagy leads to reduced granzyme B clearance, suggesting that Vps4b or Atg5 depletion facilitates tumor cell lysis by CD8+ T cells through enhanced granzyme B accumulation." (PMID 35379808, 2022). "Consistently, a decrease in the proliferation marker, Ki-67, was observed in SMGs from tumor-bearing Atg5flox/flox mice compared to those SMG from tumor-bearing Atg5+/+ mice." (PMID 35966597, 2022). "The Atg5 KO cells also exhibit a decreased proliferation and migration capacity, which is in agreement with the direct role of autophagy in tumor cell migration through the recycling of components of the cell migration machinery." (PMID 40396018, 2022).
tumor (continued). "Subsequently, we developed a syngeneic orthotopic MST tumor model in Atg5+/+ and Atg5flox/flox mice and revealed that Atg5flox/flox mice suppressed orthotopically allografted MST cells." (PMID 35966597, 2022). "In conclusion, TINCR can promote LCSC self-renewal and tumor progression by autophagy activation through PTBP1/ATG5 regulatory pathway." (PMID 36385098, 2022). "The inhibition of autophagy through genetic ablation of ATG5 inhibits tumor growth in colon cancer-derived cells and CRC patient-derived enteroid models." (PMID 35912261, 2022). "In whole-body Atg7 or Atg5 KO mice, circulating arginine levels are decreased, resulting in suppressed tumor growth." (PMID 35646940, 2022). "These immunocompetent Atg5+/+ mice fed with high glutamine diet developed significantly smaller tumors after orthotopic tumor implantation." (PMID 35966597, 2022). "Strategies such as gene silencing, especially ATG5 gene by a pharmacological agent, have been reported as an effective treatment for resistant tumor cells." (PMID 34947979, 2021). "Based on the evaluation of TGCA-LUSC database, we confirmed that the ATG5 expression was higher in tumor tissue than normal tissue." (PMID 34253689, 2021). "ATG5 silencing impaired OXPHOS and reduced mitochondrial function, but similar glycolysis rates and glycolytic capacity, reflected by the extracellular acidification rate, were observed between primary Atg5 KO and Atg5 WT tumor cells." (PMID 34831462, 2021). "The activation mechanism of autophagy in the tumor cells involves the upregulation of Atg5, Beclin-1, and LC3II and downregulation of p62 protein expression." (PMID 34675987, 2021). "ATG5 is a key factor involved in autophagosome formation and has various biological roles such as regulating autophagosome formation and inhibiting tumor generation." (PMID 34696663, 2021). "Full-length ATG5 mRNA expression is lower in tumor tissues in several cancer types compared to normal tissues." (PMID 33926066, 2021). "The comprehensive pan-cancer analysis not only revealed the potential of ATG5 in tumor-targeted therapy but also suggested ATG5 as a promising tumor predictive biomarker in most solid tumors." (PMID 33842365, 2021). "In other tumor cell types, we have shown that drug combinations that elevate Beclin1 and ATG5 expression and enhance autophagosome formation can reduce the levels of multiple HDAC proteins." (PMID 33898322, 2021). "Knock down of ULK1, ATG5 or Beclin1 significantly reduced tumor cell killing by the drug combination." (PMID 33898322, 2021). "It was reported that Beclin1−/− mice die early in embryogenesis and aging; mice with Beclin1+/− are tumor-prone, whereas mice with Atg5−/− and Atg7−/− are born normally, but die soon due to low nutritional level and suckling defects in neonates." (PMID 33628386, 2021). "Using TMAs containing 237 RCCs and 18 normal kidney tissues, however, we found a reduction in the protein expression of ATG1 and ATG5 in the tumor compared with the normal tissues by IHC staining." (PMID 31959887, 2020). "Aspirin enhanced the chemotherapy-induced release of ATP from tumor cells, and this effect was lost upon knockdown of the essential autophagy gene Atg5." (PMID 33298861, 2020). "Interestingly, a reversible RNAi mouse model that targets Atg5 expression showed that, while extended autophagy inhibition can accelerate ageing, reactivating autophagy after a period of inhibition can cause increased frequency of spontaneous tumour development." (PMID 32873152, 2020). "In vivo, NOD/SCID mice injected with tumor cells with stable Atg5 interference developed significantly more extensive macroscopic lung metastases." (PMID 32811814, 2020). "His group also found higher ATG5 expression tumor group had worse prognosis including the overall survival (OS) and progression-free survival (PFS)." (PMID 32998713, 2020).
tumor (continued). "Some studies indicate that overexpression of ATG5 sensitizes tumor cells to chemotherapy, and knockout of this protein increases tumor cell resistance to chemotherapeutic drugs." (PMID 33194736, 2020). "ATG5, as one of the critical regulators of autophagy, can be regulated by various genes contributing to tumorigenesis, tumor progression, and chemo-/radio-resistance." (PMID 32974198, 2020). "Compared with normal tissues, tumor tissues showed significantly higher mRNA levels of the following key autophagy genes: ATG5, ATG7, ATG3, ATG9A, ATG9B, ATG12, AMBRA1, and NBR1." (PMID 32582551, 2020). "Upregulated ATG5 expression was positively correlated with male, advanced tumor (T) stage, and TNM stage." (PMID 32974198, 2020). "Delineating why depletion of ATG5 or other key autophagy proteins in TECs instead further aggravates tumor angiogenesis is mandatory to define a role for autophagy in this crucial stromal compartment." (PMID 30692642, 2019). "Although oncogenic RAS-expressing atg5−/- or atg7−/- cells display reduced tumor growth, we found that CDH1 expression was largely reduced in oncogenic RAS-expressing atg7−/- or atg5−/- tumors compared to oncogenic RAS-expressing Atg7+/+ or Atg5+/+ tumors." (PMID 30782064, 2019). "Combining with all experimental data above, PAX5-activated IDH1-AS1 acted as an oncogene in PCa tumor growth by promoting ATG5-induced autophagy." (PMID 31570703, 2019). "Similar results have been observed in mice with systemic mosaic Atg5 deletion or liver-specific deletion of Atg7, which led to the development of benign liver adenomas." (PMID 31554173, 2019). "Dysregulation of this conjugation switch through multiple mechanisms in human tumors highlights the importance of ATG5 as a critical regulator of autophagy, and is consistent with the purported role of autophagy as a suppressor of tumor initiation." (PMID 31636955, 2019). "HCT116 and Caco-2/15 cells, both of which exhibited high autophagic flux under glucose starvation in vitro, were sensitive to autophagy inhibition and showed a 50% decreased tumor growth upon ATG5 or RAB21 depletion." (PMID 31383875, 2019). "Collectively, these results indicate that ATG5 or RAB21 depletion in CRC cells can either inhibit or promote tumor growth." (PMID 31383875, 2019). "While full-length ATG5v1 was the dominant species in all tumor types, we found a statistically significant reduction in the percentage of full-length ATG5 expression in 6 out of 12 tumor types (p < 0.01)." (PMID 31636955, 2019). "On the contrary, genetic depletion of Atg5 in ECs worsens both structural and functional features of the vessels, exacerbating the chaotic and functionally abnormal tumor vasculature." (PMID 30692642, 2019). "Contrary to results obtained in vitro, depletion of either ATG5 or RAB21 markedly affected tumor growth." (PMID 31383875, 2019). "Our results proved that silence of ATG5 enhanced the positive wound healing and inhibited metastatic spread of tumor cells, finally indicating downregulation of ATG5 alleviates HIF1α-induced metastasis in PCa." (PMID 31700698, 2019). "In this study, despite displaying reduced tumor growth, HRasV12 expressing atg5−/− or atg7−/− tumors had increased EMT marker expression, which was reverted using a NF-κB inhibitor." (PMID 31554173, 2019). "Deletion of ATG-5 in the pancreas has been shown to increase tumor initiation but decrease tumor progression indicating a tumor stage-dependent action of autophagy." (PMID 31921387, 2019). "Collectively, the focus of this study is on exploring the role of PAX5-activated IDH1-AS1 in PCa tumor growth via ATG5-induced autophagy." (PMID 31570703, 2019). "We also performed a permanent inhibition of cell-intrinsic macro-autophagy by a stable knockdown of ATG5 in tumor cells." (PMID 29774126, 2018).
tumor (continued). "In order to determine the role of autophagy in tumor dormancy or relapse, we used shRNA for a stable knockdown of ATG5 (ATG5KD) which inhibits formation of autophagosomes in MMC." (PMID 29774126, 2018). "Ras-mutated tumours have shown an increased dependency on the autophagic process in vitro and in vivo, and knockdown of autophagy-related genes Atg5 and Atg7 limited tumour growth." (PMID 30182146, 2018). "A stable knockdown of cell-intrinsic autophagy by ATG5 shRNA resulted in a reduced sensitivity of tumor cells to chemotherapy- or T cell-induced apoptosis, and accelerated tumor relapse in vivo." (PMID 29774126, 2018). "On the other hand, no statistically-significant difference in this ratio was observed between the wild-type and knockout tumors for TNP-2 + NIR treatment (43.82% for wild-type tumor and 47.08% for Atg5 knockout tumor, p > 0.05, Student’s t-test)." (PMID 30315154, 2018). "Mutations and reduced expression of Atg5 were found in many gastrointestinal carcinomas including CRC, suggesting the tumor suppressor role of autophagy in CRC." (PMID 29643976, 2018). "Specific hepatocyte Atg5 knockout mice revealed the tumor promoter role of autophagy in hepatocarcinogenesis." (PMID 29643976, 2018). "ATG5 overexpression promotes tumor cell sensitivity to chemotherapy, whereas inhibition of ATG5 increases resistance to chemotherapy." (PMID 28208579, 2017). "Regarding tumor cell survival, the resistance to metabolic stress induced by TMEM74 overexpression was counteracted by ATG5, ATG7, ATG16L1, ATG3 and ATG10 deficiencies but not the BECN1 and ULK1." (PMID 29048433, 2017). "Meanwhile, ATG5 expression was significantly higher in ESCC tumor tissues than in adjacent normal tissue." (PMID 29207660, 2017). "siRNA-mediated knockdown of Atg5 combined with ursolic acid treatment in TC-1 tumor cells attenuated LC3 II accumulation, as shown by Western blotting, implying that the ursolic acid-induced autophagy relies on Atg5." (PMID 29209152, 2017). "Higher expression of ATG5 in both normal and tumor esophageal tissues had a trend to correlate with adverse clinical outcome of patients." (PMID 29207660, 2017). "The expression of ATG5 was significantly up-regulated in tumor tissues compared to its expression in adjacent normal tissue (P<0.001, independent t-test)." (PMID 29207660, 2017). "The intracellular level of autophagy in oncolytic adenovirus-infected tumor cells can be evaluated by analyzing changes in autophagy-related biomarkers, such as upregulation of Atg5 and LC3-II, p62 downregulation, and the formation of cytoplasmic AVOs." (PMID 28698504, 2017). "Either treatment with an autophagy inhibitor or silencing of ATG5 partially reversed the sensitizing effect of metformin on TRAIL-induced tumor cell death." (PMID 28895911, 2017). "For example, the deletion of Beclin 1, ATG5, or ATG7 were found to associate with the tumor phenotype of HCC." (PMID 28915706, 2017). "ATG5 is thus a possible factor involved in the tumor recurrence in early-stage esophageal cancer, yet it has hardly been investigated." (PMID 29207660, 2017). "In CR-fed mice, Atg5+/+ tumor incidence was 71 % (10/14;) and Atg5−/− tumor incidence was 14 % (2/14)." (PMID 27651895, 2016). "The ATG5 gene product is an E3 ubiquitin ligase involved in elongation of autophagosomal membranes that facilitates tumor survival in nutrient deprivation." (PMID 27120789, 2016). "Despite that Beclin1 having been demonstrated as having a tumor-suppression function for autophagy, KO of Atg5, Atg7 and FIP200, other essential autophagy proteins, failed to initiate malignant tumor development in vivo." (PMID 27124579, 2016). "No diet-dependent difference in the percent of cells with LC3 puncta was detected in tumors obtained 4 weeks after mice were transplanted with Atg5+/+ tumor cells." (PMID 27651895, 2016).